PARP3 (poly(ADP-ribose) polymerase family member 3)
Diseases named in the same sentence as PARP3 in open-access papers (continued):
Sharing a sentence is not in itself a finding about the gene and the disease.
lung carcinoma (4 papers, 2014 to 2025). "Emerging evidence also implicates PARP-2 and PARP-3 in carcinogenesis, with PARP-3 located at chromosome 3p21.1-3p21.31-a region frequently affected by loss of heterozygosity in early-stage lung cancer." (PMID 41294806, 2025). "PARP3 mRNA levels were increased in a time-dependent manner in the lung cancer cell line A549, the hepatocellular carcinoma cell line HepG2 and the mammary epithelial cell line MCF10A after TGFβ stimulation." (PMID 27579892, 2016). "In this work, we observed that PARP3 depletion in lung cancer cells resulted in increased telomerase activity." (PMID 24528514, 2014). "Moreover, the inhibition of PARP3 in lung cancer cells and osteosarcoma cells was found to increase telomerase activity, promote telomere maintenance, and lessen gene instability." (PMID 37350936, 2023).
brain cancer (2 papers, 2022 to 2024). A primary or metastatic malignant neoplasm affecting the brain. "We first compared the expression of PARP3 in a series of human brain cancer cell lines." (PMID 36109561, 2022).
epithelial ovarian cancer (2 papers, 2017). "Co-treatment of VPA with DOX led to synergistic suppression of cell viability with an increase in caspase-3 activity and CDKN1A, CCNE1, PARP1, and PARP3 proteins expression in ovarian cancer cell lines." (PMID 28498322, 2017).
acute myeloid leukemia (1 paper, 2020). Acute myeloid leukemia (AML) is a group of neoplasms arising from precursor cells committed to the myeloid cell-line differentiation. "Our research suggests that there is a different regulation of PARP1, PARP2, PARP3, and TRPM2 genes expression in acute myelogenous leukemia cells." (PMID 32423430, 2020). "Our research suggests that there is a different regulation of PARP1, PARP2, PARP3, and TRPM2 gene expression in acute myelogenous leukemia cells." (PMID 32423430, 2020).
diffuse large B-cell lymphoma (1 paper, 2021). "PARP3 and PARP9 are overexpressed in different human cancer tissues such as BC, cervical cancer (CC), and diffuse large B-cell lymphoma (DLBCL), whereas PARP7 expression is decreased in cancer tissues." (PMID 34976832, 2021).
leukemia (1 paper, 2025). A malignant (clonal) hematologic disorder, involving hematopoietic stem cells and characterized by the presence of primitive or atypical myeloid or lymphoid cells in the bone marrow and the blood. "Targeting PARP3 may achieve a potential anti-leukemia effect by disrupting migration and cell growth." (PMID 41008918, 2025). "Therefore, we hypothesize that targeting PARP3 may achieve a potential anti-leukemia effect by disrupting genomic stability and cell growth." (PMID 41008918, 2025).
melanoma (1 paper, 2021). A malignant, usually aggressive tumor composed of atypical, neoplastic melanocytes. "A microarray analysis of the syngeneic murine melanoma model B16F10 upon a dual treatment of carbon-ion external radiotherapy and 131I-Benzamide showed an enrichment of the genes PARP3, MDM2, GADD45A, which were also found to be upregulated in our study." (PMID 34830750, 2021).
multiple sclerosis (1 paper, 2011). A progressive autoimmune disorder affecting the central nervous system resulting in demyelination. "As well, a recent study in a mouse model of multiple sclerosis showing a robust upregulation of PARP3 expression in the spinal cord of mice developing the symptoms of the disease also suggests a role for PARP3 in the central nervous system." (PMID 21264220, 2011).
neuroblastoma (1 paper, 2011). Neuroblastoma (NB) is the most common solid, extracranial childhood tumor. "It led us to examine the functions of PARP3 during vertebrate development using zebrafish as a model system and to identify genes associated with PARP3 in the human neuroblastoma cell line SK-N-SH." (PMID 21264220, 2011). "In contrast to expression levels beyond detection limits in many human cell lines, PARP3 expression in the neuroblastoma cell line SK-N-SH permits a detailed cellular analysis." (PMID 21264220, 2011). "We demonstrate that PARP3 gene occupancy in the human neuroblastoma cell line SK-N-SH occurs preferentially with developmental genes regulating cell fate specification, tissue patterning, craniofacial development and neurogenesis." (PMID 21264220, 2011).
non-small cell lung carcinoma (1 paper, 2014). A group of at least three distinct histological types of lung cancer, including non-small cell squamous cell carcinoma, adenocarcinoma, and large cell carcinoma. "In order to validate these data, we evaluated telomerase activity and PARP3 expression in a cell line from similar origin, such as H522 (stage 2, adenocarcinoma, non-small cell lung cancer)." (PMID 24528514, 2014).
ovarian tumors (1 paper, 2023). "Rucaparib is a well-known inhibitor of PARP-1, PARP-2, and PARP-3 enzymes that is clinically used for the treatment of certain types of ovarian tumors." (PMID 36768904, 2023).
prostate carcinoma (1 paper, 2021). A carcinoma that arises from epithelial cells of the prostate gland. "Olaparib is inhibiting PARP1, PARP2, and PARP3 and is used as a therapy for cancer in people with hereditary BRCA1 or BRCA2 mutations, which include some ovarian, breast and prostate cancers." (PMID 33481867, 2021).
sarcoma (1 paper, 2021). A usually aggressive malignant neoplasm of the soft tissue or bone. "PARP3 and PMS1, which were genes associated with a better PFS of trabectedin, were overexpressed in L‐sarcomas and in tumors with a somatic location, whereas PARP1, a gene that correlated with worse PFS of trabectedin, was highly expressed in non‐L‐sarcomas and tumors with visceral location." (PMID 33983674, 2021). "Noteworthy, PARP3 seems to be overexpressed in tumors that benefit from trabectedin treatment (i.e., L‐sarcomas and tumors with somatic location), while PARP1 expression is higher in sarcomas with lower activity of trabectedin (non‐L‐sarcomas and tumors with visceral location)." (PMID 33983674, 2021).
Stroke (1 paper, 2020). Sudden impairment of blood flow to a part of the brain due to occlusion or rupture of an artery to the brain. "Moreover, given the altered mTorc2 signaling after cerebral hypoxia-ischemia detected here and the role of oxidative stress to stroke injury, we may speculate that Parp3–/– mice are more vulnerable to HI." (PMID 33159039, 2020).
cancer (26 papers, 2014 to 2025). A tumor composed of atypical neoplastic, often pleomorphic cells that invade other tissues. "Although, PARP3 has been reported to be associated with cancer, research data on the crosstalk between PARP3 and inflammatory diseases is lacking to date." (PMID 40461998, 2025). "For example, PARP3, 9 are overexpressed in different types of human cancers, including BRCA1-associated cancers and DLBCL." (PMID 35652091, 2022). "The results of the pathway enrichment analysis conducted on the upregulated DEGs indicated that PARP3 primarily upregulated signaling pathways associated with “cancer”, “cell survival and apoptosis”, and “signal transduction and interaction”, and “energy metabolism”." (PMID 41008918, 2025). "Moreover, PARP3, have been found to be associated with BC and can exhibit anti-cancer effects by inhibiting Akt dephosphorylation." (PMID 39877345, 2024). "Moreover, RB1 mutation had SL interaction with PARP3 knockdown in the RNA interference screening data set (Cancer Dependency Map [DepMap] Portal, Achilles)." (PMID 37937640, 2023). "Therefore, PARP3 and BRCA1 are synthetic lethal, and targeting the catalytic activity of PARP3 might be a promising therapeutic strategy for BRCA1-associated cancers." (PMID 34976832, 2021). "PARP3 is not only involved in the repair of DNA damage in cancer cells but also regulates cell mitosis." (PMID 40461998, 2025). "Poly(ADP-ribose) polymerase 3 (Parp3) is known for its role in DNA repair, mitotic division, and cancer aggressiveness." (PMID 40248123, 2025). "Beyond the current study, PARP3 has been shown to be aberrantly expressed in multiple human cancers." (PMID 41008918, 2025). "In human cancer cells, Parp3 was found to interact with and ADP-ribosylate the histone H3 lysine 9 methyltransferase G9a to restrain the G9a-dependent repression of adhesion and hypoxia-responsive genes." (PMID 40248123, 2025). "PARP-3 inhibition increases telomerase activity, which can be beneficial in treating cancers like NSCLC where telomere attrition has been documented to be associated with a poorer prognosis due to a higher incidence of chromosomal rearrangements." (PMID 33922595, 2021). "PARP-3 inhibition is a cancer therapy target based on its involvement in mitosis progression that also depends on telomere integrity." (PMID 33922595, 2021). "If so, the relevance of PARP3 inhibition in clinical therapeutic trials for cancer treatment has to been taken with care." (PMID 33159039, 2020). "We have previously identified a role of PARP3 in the TG2-Snail-E cadherin axis in cancer progression, a signaling pathway driven by NF-kB27." (PMID 33159039, 2020). "In view of the critical importance of cancer stem cells in tumor dissemination, the observation that PARP3 promotes stem-like cell characteristics supports our initial observation that invasive basal-like cancer cell lines express higher basal levels of PARP3." (PMID 27579892, 2016). "Considering previous result in Non-Small Cell Lung Cancer (NSCLC), we investigated in human cancer cells the role of PARP3 in the regulation of telomerase activity." (PMID 24528514, 2014). "PARP3 has been proposed as a new, potential target to suppress centrosome clustering, with interest in cancer therapy." (PMID 24528514, 2014). "Given that PARP3 inhibitor is currently used to treat cancer." (PMID 40461998, 2025). "Collectively, these results imply that PARP3 may represent a potential novel target for overcoming various malignant tumors." (PMID 41008918, 2025). "Furthermore, PARP3 improves the DNA repair ability and genomic stability of cancer cells by assisting the NHEJ process." (PMID 38351531, 2024).
cancer (continued). "PARP3 could be potential target for anticancer therapies and its inhibiting may increase the effectiveness of cancer treatment by reversing the EMT‐mediated chemoresistance in NSCLC." (PMID 38351531, 2024). "In addition, PARP3 enhances the DNA repair proficiency and genomic stability of cancer cells by supporting the NHEJ process." (PMID 38351531, 2024). "Although PARP3 is a target in cancer therapy, no previous study has revealed an association with AD." (PMID 32816243, 2020). "What is not yet clearly defined is the biological interest of targeting PARP3 in cancer therapy." (PMID 27579892, 2016). "At this respect, our data indicate that, at least in some cancer cells, repression of PARP3 could be responsible for an increased telomerase activity, this fact could contribute to telomere maintenance, and avoid genome instability." (PMID 24528514, 2014). "Both functions open stimulating prospects for specifically targeting PARP3 in cancer therapy." (PMID 24528514, 2014). "In contrast, PARP-3 mRNA was down-regulated in cancer cells compared to normal cells." (PMID 25139788, 2014). "Our data indicated that, at least in some cancer cells, repression of PARP3 could be responsible for an increased telomerase activity, this fact contributing to telomere maintenance and, therefore, avoiding genome instability." (PMID 24528514, 2014). "PARP3 may gain relevance as a therapeutic target in cancer treatment." (PMID 32603365, 2020). "Consequently, our findings support the idea that targeting PARP3 may have a clear potential benefit to restrain cancer related TGFβ-promoted EMT and may be used as an advantage to target cancer stem cells." (PMID 27579892, 2016). "Moreover, in cancer cells with low telomerase activity, PARP3 showed high expression levels." (PMID 24528514, 2014). "However, the usefulness of PARP3 inhibition in cancer therapy should also consider that repression of PARP3 could increase telomerase activity levels with a clear relation to a proliferative advantage in cancer cells." (PMID 24528514, 2014). "The development of poly (ADP-ribose) polymerase inhibitors (PARPi) represents a novel approach to cancer treatment, targeting PARP1, PARP2, and PARP3 proteins crucial in repairing single-strand DNA breaks." (PMID 38910707, 2024). "PARP3 is involved in the ROS signaling pathway activated by TGFβ, which leads to EMT and stemness in cancer cells." (PMID 38351531, 2024). "According to previous studies, PARP3 participates in the ROS signaling pathway triggered by TGFβ, which promotes EMT and stemness in cancer cells." (PMID 38351531, 2024). "In contrast, PARP-3 and telomerase expression negatively correlate in NSCLC and in various cancer cell lines." (PMID 33922595, 2021). "In this review, we summarize the role and regulatory mechanism of PARP3, PARP4, and PARP6–16 in cancer." (PMID 34976832, 2021). "For example, PARP3 (P = 0.4128) has been reported to contribute to tumor progression, and NR2F2 (P = 0.3383) has been identified as a critical regulator of malignant cancer stem cell functions." (PMID 40279344, 2025). "Thus, we suspect that the novel interaction of BAP1 and PARP3 may also be perturbed by PARP inhibitors, leading to inhibition of cancer growth." (PMID 33916178, 2021). "Similarly to PARP3, although with distinct functions, G9a in complex or not with GLP1, has been shown to mediate the repair of double-strand breaks, to play critical roles in development and to promote cancer progression." (PMID 36109561, 2022).
tumor (21 papers, 2012 to 2025). "Gene Ontology (GO) enrichment analysis indicated that PARP3 is associated with cellular organelle organization, cell motility, developmental processes, signal binding, and metabolic regulation, all of which critically contribute to tumor growth and migration." (PMID 41008918, 2025). "As HR loss has been demonstrated to result in mutagenesis, PARP3-directed enhanced HR repair could potentially halt tumour progression by promoting genomic stability." (PMID 34440228, 2021). "Similarly to PARP3, G9a has been associated with tumor aggressiveness." (PMID 36109561, 2022). "Nonetheless, we found 46 genes that carried either genomic or transcriptional alterations in all three resistant tumor groups, including 8 genes (Parp3, Gstm1, Il18, Padi4, Dnmt3b, Psrc1, Rif1, and Ankrd26) involved in DDR." (PMID 37209095, 2023). "Within the irradiated group, we found downregulation of UNG, FEN1, PARP3, POLD, NTLH1, ERCC1 and MPG which are linked to increased DSBs, sensitivity to alkylating agents, impaired tumor growth and reduced EMT, DSB repair and mitotic progression." (PMID 34680264, 2021). "More recently, PARP3 has also been defined for its contribution in tumor aggressiveness exemplifying its selective inhibition as an encouraging therapeutic strategy for chemo-resistant breast cancers." (PMID 33159039, 2020). "In the present study, we analysed the expression of PARP1, PARP2 and PARP3 genes in a panel of RMS primary tumours and cell lines, and evaluated the biological and molecular effects of PARP inhibition in RMS in vitro models by using Olaparib or AZD2461." (PMID 30357520, 2019). "Transcript levels of PARP1, PARP2 and PARP3 genes were evaluated in a panel of 17 RMS primary tumours (4 ARMSs and 13 ERMSs) by quantitative Real Time PCR (q-PCR) experiments." (PMID 30357520, 2019). "To further study the importance of PARP3 in breast stem cell activity, we used the tumor spheroids forming assay to evaluate the capacity for mammosphere formation in non-adherent serum-free conditions." (PMID 27579892, 2016). "PARP3: Among MARTs that promote tumor development, PARP3 is one of the best characterized." (PMID 41463260, 2025). "PARP3 knockdown significantly suppresses the metastasis-promoting proteins Vimentin and N-cadherin, while concomitantly upregulating the expression of the epithelial tumor suppressor E-cadherin." (PMID 41008918, 2025). "Currently, research on PARP3 and the tumor immune microenvironment is still limited." (PMID 37350936, 2023). "Dr. Dantzer’s group has made considerable progress in this field, attributing relevant functions to PARP3 and its MART activity in tumor progression and differentiation." (PMID 41463260, 2025). "Due to their role in HR promotion, high PARP3 levels are expected to result in enhanced repair of CRT-induced damage, leading to poor therapeutic responses, tumour progression and a poorer prognosis." (PMID 34440228, 2021). "Parp3 is a member of the Poly(ADP-ribose) polymerase (Parp) family that has been characterized for its functions in strand break repair, chromosomal rearrangements, mitotic segregation and tumor aggressiveness." (PMID 33159039, 2020). "Cells are able to tolerate HR inhibition equally well in the presence or absence of PARP3, in keeping with the observations that AZD2461, a compound that inhibits PARP1 and PARP2 but not PARP3, effectively causes BRCA-mutated tumour regression." (PMID 29467415, 2018). "Selective PARP3 inhibitors could represent a tractable strategy to combine with G4 DNA ligands to exacerbate G4 DNA formation, DSB induction and tumour cell death." (PMID 28447610, 2017). "In addition, we found that the expression of hsa-miR-98-3p in tumor tissues was significantly higher than that in adjacent tissues (wilcoxon rank sum test, p < 0.001) in patients with BRCA, but PARP3 showed the opposite expression pattern (wilcoxon rank sum test, p < 0.001)." (PMID 35479398, 2022).
infection (1 paper, 2025). The state of being infected such as from the introduction of a foreign agent such as serum, vaccine, antigenic substance or organism. "We identified 7 Parp genes that were upregulated in OBs following both WT and N1347A JHMV infection, including Parp3, 7, 9, 10, 11, 12, 13, and 14, again with their expression slightly lower but not statistically different from WT infection." (PMID 40471948, 2025).
PARP3 also shares sentences with these, for which no sentence is quoted: adenocarcinoma (1 paper); astrocytoma (1); cardiac hypertrophy (1); colorectal cancer (1); Ewing sarcoma (1); Fanconi anemia (1); glioma (1); Hepatitis (1); hepatocellular carcinoma (1); liver cancer (1); osteosarcoma (1); ovarian cancer (1); pancreatic cancer (1); viral infection (1).